ADNP (activity dependent neuroprotector homeobox)
Description:
May be involved in transcriptional regulation. May mediate some of the neuroprotective peptide VIP-associated effects involving normal growth and cancer proliferation. Positively modulates WNT-beta-catenin/CTNN1B signaling, acting by regulating phosphorylation of, and thereby stabilizing, CTNNB1. May be required for neural induction and neuronal differentiation. May be involved in erythroid differentiation (By similarity).
Synonyms: ADNP1; KIAA0784; HVDAS; MRD28
Tractability: PROTAC: UniProt records ubiquitination sites on it; ubiquitination databases record sites on it; its protein half-life has been measured.
Gene: Protein-coding gene on chromosome 20 (50,888,916 to 50,931,437, reverse strand). Ensembl gene ENSG00000101126.
Subcellular location: Nucleus; Chromosome
Subcellular location (Human Protein Atlas): Centrosome; Nucleoplasm; Basal body; Primary cilium; Primary cilium tip
Pathways (Reactome):
Chromatin organization: ChAHP complex assembly
Gene Ontology:
Molecular function: protein binding; DNA-binding transcription factor activity, RNA polymerase II-specific; RNA polymerase II transcription regulatory region sequence-specific DNA binding; beta-catenin binding; beta-tubulin binding; chromatin binding; copper ion binding; DNA binding; peptide binding
Biological process: regulation of gene expression; regulation of transcription by RNA polymerase II; cGMP metabolic process; estrous cycle; intracellular nitric oxide homeostasis; negative regulation of gene expression; negative regulation of neuron apoptotic process; negative regulation of synaptic transmission; neuron differentiation; positive regulation of axon extension; positive regulation of canonical Wnt signaling pathway; positive regulation of neuron projection development; positive regulation of synapse assembly; regulation of nitric oxide metabolic process; response to carbohydrate; short-term memory
Cellular component: RNA polymerase II transcription regulator complex; chromatin; chromosome; nucleoplasm; nucleus; axon; dendrite; extracellular region; neuronal cell body
Genetic constraint (gnomAD): Loss-of-function variants: 4 observed, 86.21 expected, observed/expected ratio (o/e) 0.0464, 90% interval 0.022 to 0.11. The upper end of that interval is the gene's LOEUF score, 0.11, which puts it in group 1 of 6, group 1 being the genes least tolerant of losing a copy. Missense variants: 1,118 observed, 1,380.9 expected, observed/expected ratio (o/e) 0.81, 90% interval 0.77 to 0.85. Synonymous variants: 551 observed, 492.59 expected, observed/expected ratio (o/e) 1.12, 90% interval 1.04 to 1.2.
Gene-disease validity (ClinGen):
ClinGen rates the evidence that ADNP causes each of these diseases.
ADNP-related multiple congenital anomalies - intellectual disability - autism spectrum disorder (autosomal dominant): Definitive.
Homologues: Orthologues: chimpanzee ADNP (99% identical), dog ADNP (98% identical), pig ADNP (98% identical), guinea pig ADNP (97% identical), macaque ADNP (97% identical), mouse Adnp (94% identical), rat Adnp (94% identical), rabbit ADNP (93% identical), tropical clawed frog adnp (72% identical), zebrafish adnpb (50% identical). Paralogues in human: ADNP2 (24% identical).
Diseases named in the same sentence as ADNP in open-access papers:
ADNP is named in the same sentence as 121 diseases in open-access papers, as found by Europe PMC text mining. Sharing a sentence is not in itself a finding about the gene and the disease. The quoted sentences say what the papers report.
autism (43 papers, 2015 to 2025). Persistent deficits in social interaction and communication and interaction as well as a markedly restricted repertoire of activity and interest as well as repetitive patterns of behavior. "The UPR is also involved in a broad spectrum of disorders associated with ADNP dysfunction, including autism, schizophrenia, Alzheimer’s disease and other late-onset neurodegenerative disorders." (PMID 39715923, 2025). "As such, de novo mutations in ADNP lead to syndromic autism and somatic ADNP mutations parallel Alzheimer’s disease progression." (PMID 39715923, 2025). "Given that ADNP is a high-confidence ASD gene mutated in syndromic autism, we validated the ADNP–POU3F2 interaction via co-immunoprecipitation in HEK293T cells." (PMID 40498903, 2025). "ADNP gene mutations typically result in a syndromic form of autism, co-morbid with ID, termed Helsmoortel–Van der Aa syndrome." (PMID 38637827, 2024). "In subsequent screening studies using whole-exome or molecular inversion probes in large cohorts of patients with ID and or autism in large cohorts of thousands of patients, ADNP is consequently among the most frequently mutated genes observed." (PMID 36945042, 2023). "In this review, we discussed the current knowledge of the chromatin remodeler ADNP, a gene frequently mutated in syndromic autism." (PMID 36945042, 2023). "From an animal model perspective, ketamine administration, like ADNP deficiency (mutations) has been suggested to model autism and schizophrenia in rodents." (PMID 37759476, 2023). "Constitutional stop and frameshift mutations in ADNP cause a form of syndromic autism referred to as the Helsmoortel–Van der Aa syndrome." (PMID 36945042, 2023). "In this review, we summarize available information on one of the most frequently mutated genes in syndromic autism the Activity-Dependent Neuroprotective Protein (ADNP)." (PMID 36945042, 2023). "Heterozygous and predicted loss-of-function ADNP mutations in individuals inevitably result in the clinical presentation with the Helsmoortel–Van der Aa syndrome, a frequent form of syndromic autism." (PMID 36945042, 2023). "Genome-wide whole-exome studies in patients with autism co-morbid with intellectual disability (ID) revealed an excess of truncating de novo mutations in the ADNP gene is (p = 0.001852, odds ratio = 13.24668, one—sided Fisher’s exact test)." (PMID 36945042, 2023). "The ADNP gene has been found to be mutated in significant percentage of patients diagnosed with syndromic autism or intellectual disability and is one of its more frequent genetic causes." (PMID 36945042, 2023). "A leading gene presenting heterozygous dominant de novo autism-intellectual disabilities (ID) causing mutations is activity-dependent neuroprotective protein (ADNP), with intact ADNP protecting against AD-tauopathy." (PMID 31664177, 2021). "As such, ADNP mRNA content dysregulation has been implicated not only in autism but also in schizophrenia, Parkinson’s disease and AD." (PMID 31664177, 2021). "We discovered a genomic autism ADNP mutation (c.2188C>T) in postmortem AD olfactory bulbs and hippocampi." (PMID 31664177, 2021). "SNVs in the autism-associated gene ADNP (activity-dependent neuroprotective protein) occurred more frequently in AD than in controls, with increased SNV frequency associated with increased tau burden." (PMID 34356087, 2021). "In ~0.17% of the autism-intellectual disabilities (ID) cases, activity-dependent neuroprotective protein (ADNP) is mutated de novo, representing one of the most prevalent mutated heterozygous dominant genes leading to autism/ID." (PMID 31664177, 2021). "Activity-dependent neuroprotective protein (ADNP), associated with autophagy, represents another common target for the management of autism, Alzheimer’s disease, and schizophrenia." (PMID 34827633, 2021).
autism (continued). "Overlapping all tested brain areas identified unique and shared mutations, with ADNP singled out as a gene associated with autism/ID/AD and presenting several unique aging/AD mutations." (PMID 31664177, 2021). "We then showed that ADNP interacts with the autism-linked protein eukaryotic translation initiation factor 4E (eIF4E) and further regulates it expression in males only." (PMID 32072336, 2020). "Activity-dependent neuroprotective protein (ADNP), essential for brain formation, was discovered as a leading de novo mutated gene causing the autism-like ADNP syndrome." (PMID 30664622, 2019). "Recently, de novo mutations in ADNP were identified as leading to the autism-like ADNP syndrome, mimicked by the Adnp-deficient mouse model." (PMID 31992971, 2019). "Mutations in ADNP have been linked to autism and intellectual disability, and Adnp haploinsufficiency in mice is linked to altered axonal transport and dendritic spine alterations." (PMID 31438497, 2019). "Despite shared associations with autism and intellectual disability, disruptive variants in ADNP, CHD8, and DYRK1A may yield variable psychiatric phenotypes among children and adolescents." (PMID 38622540, 2024). "Similarly, though mutations in ADNP do result in autism and to play a suggested role in cancer, the mutational mechanism remains to be further investigated." (PMID 36945042, 2023). "Additionally, some ADNP mutations, such as those that appear in p.Arg730* (autism) and the recurrent somatic ADNP frameshift mutation p.Arg730Thrfs*4 in Alzheimer’s disease post-mortem brains, are localized to caspase cleavage sites." (PMID 36230962, 2022). "Our observations provide a novel activity of the autism-linked ADNP in the skin that may serve to define the clinical phenotype of patients with ADNP syndrome and provide an attractive therapeutic option for skin alterations in these patients." (PMID 30679581, 2019). "As neurodevelopment has been linked to Tau3R, our results pave the path to the development of NAP (davunetide, CP201) for ADNP deficiencies associated with neurodevelopment, for example, the autism-like ADNP syndrome, resulting from de novo truncating mutations in ADNP." (PMID 30865715, 2019). "Despite shared associations with autism and intellectual disability, data presented here suggest ADNP, CHD8, and DYRK1A may yield variable psychiatric phenotypes among affected children and adolescents, including differential associations with early development." (PMID 38622540, 2024). "Furthermore, this steroid regulation may be linked with the higher prevalence of autism in boys compared to girls, with ADNP being a major autism driving gene." (PMID 32937737, 2020). "Together, these studies define POU3F2 as an activator of canonical Wnt signalling and mechanistically link two high-confidence autism genes, ADNP and POU3F2, in the regulation of neurodevelopment." (PMID 40498903, 2025). "We maintain that ADNP, and possibly other autism-related genes, not only regulate learning, memory, and social behavior, but also sex-related development and behaviors." (PMID 39715923, 2025). "POGZ protein enhances chromatin accessibility and expression of clustered synapse genes, and cooccurs loci with ADNP, a gene related with autism, according to analyses of POGZ knockout mice." (PMID 39775551, 2025). "All patients exhibit heterozygous de novo nonsense or frameshift stop mutations in the Activity-Dependent Neuroprotective Protein (ADNP) gene, accounting for a prevalence of 0.2% of all autism cases worldwide." (PMID 38637827, 2024). "Individuals with ADNP disruptions were reported to have a less severe social affect symptoms compared to other monogenetic or idiopathic forms of autism." (PMID 36945042, 2023). "The ADNP-gene-related Helsmoortel–Van der Aa syndrome is a rare but increasingly often reported form of syndromic intellectual disability and autism." (PMID 36553633, 2022).
autism (continued). "In searching for leading gene candidates for autism, others ranked ADNP as a lead, paralleling our findings regarding AD potentially mutated genes." (PMID 31664177, 2021). "Second, a small peptide motif called NAP—present in Activity-Dependent Neuroprotective Protein (ADNP), which is dysregulated in schizophrenia and in autism —partially alleviates cognitive impairments in MAP6 heterozygous mice." (PMID 34025352, 2021). "We singled out ADNP (a neuro-glial protein) as a case study of cytoskeleton/autism/ID/AD shared gene." (PMID 31664177, 2021). "While ADNP2 is a less studied gene compared to ADNP, recent studies have also linked ADNP2 deletion (together with other genes) to autism." (PMID 32937737, 2020). "Mutations in the SWI/SNF-complex-related gene ADNP (Activity-Dependent Neuroprotector Homeobox; OMIM 611386) cause a syndromic form of autism called Helsmoortel-van der Aa syndrome (OMIM 615873)." (PMID 30123105, 2018). "Activity-dependent neuroprotective protein (ADNP) is deregulated in Alzheimer's disease (AD) and in schizophrenia and mutated in autism." (PMID 26578950, 2015). "Our data suggest that ADNP, CHD8, and DYRK1A groups may have separable and distinct phenotypes with regard to mental health, despite their shared associations with autism and intellectual disability." (PMID 38622540, 2024). "Among the 29 TFs activated in male PD patients, ADNP, JUN, MBD3, PRDM14, and ESR1 have known associations with neurodegenerative disorders such as Alzheimer's disease, mental retardation, schizophrenia, and autism." (PMID 36414996, 2022). "Furthermore, the smallest active snippet of ADNP, an eight-amino-acid peptide NAP (NAPVSIPQ), protected against ADNP deficiencies in autism patients with Helsmoortel-Van Der Aa syndrome." (PMID 35909451, 2022). "Human sex differences in autophagy are prominent in the brain and other tissues, with sex-differential effects from genetic variation also found in the autophagy-regulating gene ADNP (Activity-Dependent Neuroprotective Protein), which, like AMBRA1, affects autism and schizophrenia risk and traits." (PMID 31687209, 2019). "Our analysis supports the role of several genes/loci associated with autism (e.g., NRXN1, ADNP, 22q11 deletion) and identified new truncating (e.g., GRIK2, ROBO1, NINL, and IMMP2L) or recessive deleterious variants (e.g., KIRREL3 and CNTNAP2) affecting autism-associated genes." (PMID 30675382, 2019). "As the mutated-ADNP phenotype is close in features to ASD,41, 42 early or altered deciduous tooth eruption timing is of interest to a range of undiagnosed children within the autism/mentally challenged spectrum." (PMID 28221363, 2017). "Mutations of ADNP, a transcription factor that is part of the SWI/SNF chromatin remodeling complex, have been identified as a cause of neurodevelopmental disorders such as autism and ADNP has been identified as a potential tumor suppressor in breast and colorectal cancers." (PMID 34379776, 2021). "In the context of other potentially related models of autism, we hypothesize an ADNP dependent effect on the microbiota composition and potential brain-gut cross-talk related effects, which in a future translational perspective might add to a patient stratification biomarker." (PMID 32072336, 2020). "Recently, co-immunoprecipitation studies showed interaction of ADNP with autophagy regulator LC39, histone deacetylase SIRT110, and autism proteins EIF4E11 and SHANK312, all of them indicating a molecular role of epigenetic mechanisms and autism." (PMID 38926592, 2024).
autism (continued). "Activity-dependent neuroprotective protein (ADNP) syndrome, also known as Helsmoortel-Van Der Aa syndrome, is a rare condition, which is diagnosed in children exhibiting signs of autism." (PMID 33329371, 2020). "With the recent finding of ADNP as being one of a small group of genes, including CHD8 and SHANK3 that appear to lead to autism in a substantial proportion of cases, the significance of our current results is enhanced." (PMID 28221363, 2017). "Moreover, we described binding of ADNP to proteins involved in autophagy (LC3), autism pathways (EIF4E/SHANK3), chromatin remodeling (BRG1/HP1/CDH4), and epigenetic modifying genes (SIRT1/HDAC2/YY1), all impacting the physiological status of the cell." (PMID 36945042, 2023). "We concentrated on activity-dependent neuroprotective protein (ADNP), a prevalent autism gene." (PMID 32661233, 2020). "Using this method, mutations in the Activity Dependent-Neuroprotective Homeobox Protein (ADNP) gene have been discovered, contributing to a neurogenetic syndrome called Helsmoortel–Van der Aa syndrome (OMIM 615873), with a prevalence of 0.2% of global autism cases." (PMID 38637827, 2024).